GDF15 (growth differentiation factor 15)
Diseases named in the same sentence as GDF15 in open-access papers (continued):
Sharing a sentence is not in itself a finding about the gene and the disease.
Hypertension (continued). "Our multiple linear regression model revealed that age, gender, smoking and systemic hypertension significantly influenced plasma GDF-15." (PMID 34048486, 2021). "Among patients with a diagnosis of hypertension, GDF-15 predicted AID and ID anaemia in 81.1 and 81.9% of cases respectively;." (PMID 32993549, 2020). "Among those with diabetic retinopathy, the prevalence of hypertension was greater and the plasma GDF-15 concentrations were significantly higher." (PMID 33239667, 2020). "We found that serum GDF-15 was correlated with impaired aortic elasticity; moreover, it turned out to be a potent predictor of an increased aortic β-index in hypertension." (PMID 31428452, 2019). "The age of our cohort and the presence of hypertension inevitably limit the scope for correlation analyses to detect links between measures of vascular function and GDF-15 levels, due to the limited range of these variables." (PMID 27734214, 2017). "We investigate the effect of plasma GDF-15 levels on left ventricular hypertrophy (LVH) in hypertension." (PMID 23071585, 2012). "Fourthly, the original studies we selected did not directly investigate the association between GDF-15 and hypertension; instead, they examined GDF-15 in relation to other medical conditions." (PMID 40371061, 2025). "Thus, the hypertension-related data extracted for this meta-analysis were limited to baseline information—specifically, the number of hypertensive patients across GDF-15 categories." (PMID 40371061, 2025). "Consequently, the results of the two-class meta-analysis, which compared hypertension prevalence between high and low circulating GDF-15 levels, should be interpreted with caution." (PMID 40371061, 2025). "However, in nonclinical populations, the prevalence of hypertension increased by 39% with every 1 ng/ml increase in GDF-15, similar to the overall pooled result." (PMID 40371061, 2025). "Circulating GDF-15 is positively and non-linearly associated with the prevalence of hypertension, with a plateau or slight decline after reaching a certain GDF-15 dose." (PMID 40371061, 2025). "However, in the multivariable model, after adjusting for all other variables, only hypertension remained a statistically significant predictor of circulating GDF15 levels." (PMID 40530451, 2025). "This dose-response meta-analysis suggested that circulating GDF-15 is positively and non-linearly associated with the prevalence of hypertension." (PMID 40371061, 2025). "The finding also suggests that exogenous GDF-15 supplementation may be advantageous for the prevention or treatment of chronic metabolic diseases, such as hypertension." (PMID 40371061, 2025). "A slight decreasing trend in the dose-response curve implies that the administration of GDF-15 may be beneficial for preventing or treating hypertension." (PMID 40371061, 2025). "Finally, this study is subject to selection bias, primarily because it included only studies that reported hypertension prevalence with at least three GDF-15 categories." (PMID 40371061, 2025). "However, to determine the efficacy and impact of GDF-15 supplementation on hypertension or other chronic diseases in humans, it is essential to conduct prospective studies, including clinical trials." (PMID 40371061, 2025). "Although there is evidence of interplay between GDF15 and metabolism, its association with hypertension has not been investigated much to date." (PMID 36992609, 2023). "In addition, these studies emphasize the role of GDF15 as mediator of vascular remodelling, which is a major feature of essential hypertension as well as PAH." (PMID 36992609, 2023). "As expected, women with hypertension at inclusion (systolic blood pressure ≥ 140 mmHg and/or diastolic blood pressure ≥ 90 mmHg) had significantly higher levels of cTnT (p < 0.001), NT-proBNP (p < 0.001) and GDF-15 (p = 0.012)." (PMID 35796791, 2022).
Hypertension (continued). "The current research indicated, for the first time, that the ApoB/ApoA1 ratio and concentrations of serum GDF-15 were predictive indicators of CAD in Chinese patients with T2DM, independent of potential risk factors such as hyperglycemia, diabetic duration, hypertension and age." (PMID 35842724, 2022). "However, our multivariable analysis showed that the statistically significant relationship between GDF-15 and diabetic retinopathy persisted despite adjustment for confounders including hypertension, HbA1c, DM duration, eGFR, and AER." (PMID 33239667, 2020). "We aimed to assess the relationship between echocardiographic parameters of aortic elasticity, namely aortic strain, aortic distensibility and aortic β-index, and serum growth differentiation factor (GDF)-15 in patients with newly diagnosed essential hypertension (HT)." (PMID 31428452, 2019). "Our results suggest that in older patients with hypertension, GDF-15 may be an independent predictor of declining physical function, but does not predict change in vascular function." (PMID 27734214, 2017). "Growth differentiation factor-15 (GDF-15) may be a biomarker of disease, protective response and/or prognosis, in older people with hypertension." (PMID 27734214, 2017). "Increasing GDF-15 was significantly correlated with black race, smoking, and hypertension." (PMID 26273671, 2015). "To test our hypothesis, we investigated the potential relationship of plasma GDF-15 levels with measures of left ventricular remodeling in patients with hypertension." (PMID 23071585, 2012). "The association between GDF-15 with LVH in hypertensive patients was also tested by the multivariate logistic regression model with the dependent variable as hypertension with or without LVH." (PMID 23071585, 2012). "Consequently, we could not adjust for confounding factors in assessing the dose-response relationship between GDF-15 and hypertension." (PMID 40371061, 2025). "Interestingly, however, although multiple studies have been done to investigate the relationship between circulating GDF-15 and the risk factors associated with hypertension, little work has been done to explore the relationship between GDF-15 and the risk of hypertension." (PMID 40371061, 2025). "However, the ability of GDF-15 to predict the risk of developing hypertension in prospective studies has not been well-studied." (PMID 40371061, 2025). "Compared to the lowest tertile (T1), subjects in the highest DNAm-predicted GDF15 tertile (T3) were typically older, exhibited a higher probability of being unmarried and self-identifying as Non-Hispanic White, and presented with a greater prevalence of hypertension and cancer history." (PMID 41398857, 2025). "Importantly, our present data indicate that the observed elevation of GDF15 levels in hypertension depends on BMI and might be an attribute of excessively obese individuals (BMI > 45 kg/m2)." (PMID 36430499, 2022). "GDF15 dynamics during weight loss—with a non-significant trend to slightly elevated concentrations after 3 months and significant reduction after 12 months—were independent of hypertension and therapeutical strategy." (PMID 36430499, 2022). "Additionally, in hypertensive patients a positive correlation between plasma GDF-15 levels and LVH was found, suggesting that GDF-15 may be involved in the development of LVH hypertension." (PMID 34920697, 2021). "Besides, serum GDF15 levels were inversely correlated with total cholesterol levels, which is also observed in 147 older people with hypertension and in 2,991 participants in the Framingham Offspring Study who were free of clinically overt cardiovascular disease." (PMID 30687235, 2018). "Compared with individuals with a low level of circulating GDF-15, those with high GDF-15 level had a higher prevalence of hypertension [odds ratios (OR) 1.60, 95% confidence interval (CI) 1.37–1.88, P < 0.001)." (PMID 40371061, 2025).
Hypertension (continued). "Compared to participants with a low GDF-15 level, those with a high GDF-15 level were significantly older, had a significantly higher prevalence of hypertension, and had significantly higher BMI and HbA1c." (PMID 39019981, 2024). "GDF-15 (p < 0.001), Troponin-T (p = 0.002), FGF-23 (p = 0.006), and IGFBP-7 (p = 0.018) abundance was higher in patients with hypertension." (PMID 35859587, 2022). "Those with a higher GDF15 level had a significantly higher prevalence of DM (p < 0.001), CKD (p < 0.001) and hypertension (p = 0.014); higher serum HbA1c (p = 0.001), HOMA-IR (p = 0.003), creatinine (p = 0.001), and urine ACR (p < 0.001)." (PMID 35683420, 2022). "Nevertheless, the dose-response curve exhibited a plateau or slight decline at higher GDF-15 concentrations, indicating that the prevalence of hypertension does not increase linearly with rising GDF-15 levels." (PMID 40371061, 2025). "These autoregulatory processes interact with intricate blood pressure regulatory networks, resulting in the nonlinear relationship between GDF-15 levels and hypertension observed in clinical settings." (PMID 40371061, 2025). "While GDF-15 is correlated with aortic stiffness and is an effective and important predictor in newly diagnosed hypertension patients, there are no current studies exploring the effect of GDF-15 on the development of premature MI." (PMID 37888100, 2023). "At the study base-line, a total of 91 patients with hypertension exhibited elevated GDF15 serum concentrations (p < 0.001) compared to those without hypertension (n = 66) (392 vs. 165 pg/mL; p < 0.001)." (PMID 36430499, 2022). "At the 12 month follow-up, the number of patients with hypertension was 56 and there was no longer a significant difference in GDF15 levels when compared to subjects without hypertension." (PMID 36430499, 2022). "Furthermore, subjects with a higher GDF15 level had significantly higher WC, HC, higher serum HbA1c, creatinine, and urine ACR, as well as a significantly higher prevalence of T2DM, CKD, and hypertension." (PMID 35683420, 2022). "Another study indicated that GDF-15 is an independent predictor of all-cause stroke and ischemic stroke (n = 12), but not ICH, in 254 patients with hypertension." (PMID 34177769, 2021). "They observed positive correlation between plasma GDF-15 levels and LVH in hypertensive patients which indicates that GDF-15 may be involved in the development of LVH in hypertension." (PMID 26273671, 2015). "A consistent positive relation between plasma GDF-15 levels and measures of LVH in hypertensive patients were observed in this study, indicating that GDF-15 may be involved in the development of LVH in hypertension." (PMID 23071585, 2012). "Both study groups examined here treated older TAVR patients with significantly increased hypertension, which was why progressive aortic stiffness could be assumed in both groups and could explain the lack of differences in the GDF-15 plasma levels." (PMID 36766463, 2023). "In addition, presence of hypertension and lifestyle factors i.e. smoking and self-reported intake of dietary supplements (by NTG patients in a subgroup analysis) contributed significantly to the variance in plasma GDF-15 concentration." (PMID 34048486, 2021). "At baseline, median GDF-15 levels were not influenced by gender (males vs. females with 776.3 vs. 764.1 pg/mL, p>0.5) but were significantly higher in patients with known arterial hypertension (854.3 vs. 571.6 pg/mL, p<0.001) and in diabetics (1142 vs. 704.9 pg/mL, p<0.001)." (PMID 28771550, 2017). "Given the rapid change of GDF-15 expression level in response to pressure overload and the important role of GDF-15 in the regulation of cardiac remodeling, we hypothesized that the circulating level of GDF-15 may involved in the development of left ventricular hypertrophy in hypertension." (PMID 23071585, 2012).
Hypertension (continued). "In agreement with this, others have found that patients with essential hypertension and left ventricular hypertrophy (LVH) had higher GDF15 concentrations compared with their counterparts without LVH or healthy patients." (PMID 36992609, 2023).
breast carcinoma (68 papers, 2007 to 2025). "GDF-15 is a candidate biomarker for increased risk of cardiotoxicity in breast cancer patients receiving neoadjuvant dual anti-HER2 therapy." (PMID 38828460, 2024). "The current study aimed to investigate the correlation of GDF-15 levels with clinical features, biochemical indices, and especially the risk of cardiotoxicity in breast cancer patients receiving neoadjuvant dual anti-HER2 therapy." (PMID 38828460, 2024). "Our current study was built on the existing studies that report the value of GDF-15 quantification in predicting cardiotoxicity risk in breast cancer patients receiving trastuzumab-based treatment." (PMID 38828460, 2024). "Overall, GDF-15 serves as a candidate biomarker for predicting an increased risk of cardiotoxicity in breast cancer patients receiving neoadjuvant dual anti-HER2 therapy." (PMID 38828460, 2024). "Regarding drug-induced cardiotoxicity in breast cancer patients, a study revealed that GDF-15 can predict the risk of cardiotoxicity in breast cancer patients receiving adjuvant trastuzumab-based anti-HER2 therapy." (PMID 38828460, 2024). "In head and neck, and breast cancer, it has been reported that the radioresistance induced by GDF15 is linked to the expression of stemness markers (CD44, Sox2, and Nanog) and the ability of cancer cells to form spheroids." (PMID 38201456, 2023). "High levels of Klhl24, Hbp1, Crebrf, Ypel2, CD22 and Ypel3 were correlated with better outcomes, whereas lower levels of Gdf15, Cdc25a, Ddit4 and Psat1 were associated with better prognosis in breast cancer patients." (PMID 34990474, 2022). "Our results suggested that NT-proBNP and HbA1C combined together, show a strong joint association with breast cancer incidence, while combining GDF-15 and HbA1C is strongly associated with lung cancer incidence." (PMID 34935094, 2022). "In contrast, lower levels of the mRNAs for Gdf15, Cdc25a, Ddit4 and Psat1 were associated with better prognosis in breast cancer patients." (PMID 34990474, 2022). "In the study, with a bioinformatics analysis of the GEO database and the survival database of breast cancer patients, we screened out the potential target molecule GDF15 associated with poor prognosis of breast cancer patients after radiotherapy." (PMID 36142823, 2022). "This study revealed that GDF15 was associated with radioresistance of breast cancer for the first time." (PMID 36142823, 2022). "By employing the TCGA database analysis of these genes, we validated that the GDF15 expression was strongly associated with the poor prognosis of 276 breast cancer patients after radiotherapy." (PMID 36142823, 2022). "Interestingly, a study reported that GDF-15 estimates the risk of cardiotoxicity in breast cancer patients receiving adjuvant therapy with trastuzumab, doxorubicin, and axanes." (PMID 38828460, 2024). "For example, GDF15 knockdown strongly suppresses HAMP mRNA (encoding hepcidin protein) in 3D culture but does not affect HAMP transcription in the 2D culture of an MCF-7 (breast carcinoma) cell line." (PMID 37296952, 2023). "However, it is known that GDF-15 also functions as a tumoral marker in cases of breast cancer being linked to occurrences of metastasis and trastuzumab resistance." (PMID 36612202, 2022). "Finally, GDF15 has been implicated in contributing to angiogenesis and the stemness of breast cancer tumors, largely through circuits that induce vascular endothelial growth factor expression and tumor sphere formation." (PMID 36353620, 2022). "In fact, it was recently shown that the link between RSU1 and GDF15 is active in brain cells similarly to what happens in breast cancer cells, in regulating cell aggressiveness, as GDF15 is known to be associated with cancer cell malignancy and is elevated in glioblastoma patients." (PMID 32517326, 2020). "As an association between visfatin and breast cancer progression has been previously established, GDF15 may likewise be used as a potential biomarker in breast cancer." (PMID 31861872, 2019).